PRL (prolactin)
Diseases named in the same sentence as PRL in open-access papers (continued):
Sharing a sentence is not in itself a finding about the gene and the disease.
tumor (continued). "Comparing across studies, 68% (median %) of patients treated with bromocriptine had normalization of prolactin levels and 62% experienced a reduction in tumor size." (PMID 22828169, 2012). "Cabergoline (CAB) is another drug belonging to the class of dopamine agonists that was approved for use in 1985 which is usually preferred over BRC due to its higher effectiveness in prolactin suppression and tumor reduction." (PMID 23110890, 2012). "It is not uncommon for patients with macroprolactinoma to have extensive cavernous sinus invasion, and the quick response to dopamine agonist therapy in terms of tumour mass reduction and normalisation of prolactin is typical for this condition." (PMID 23050176, 2012). "SRS is rarely used in the treatment of prolactinomas since medical treatment with dopamine agonists can achieve tumour shrinkage and normalize prolactin (PRL) levels in more than 80 per cent of patients." (PMID 23241206, 2012). "The effects of PRL are mediated by its receptor, and alterations in receptor expression are likely to play a role in tumor development." (PMID 22647582, 2012). "Surprisingly, in previous in vivo study, neither losartan nor PD123319 decreased the cellular proliferation in DES-induced PRL-secreting tumor in rat, although it was inhibited by angiotensin convertase inhibitor, enalaprilate." (PMID 22645419, 2012). "Trials proved that BRC lowered prolactin levels efficiently, improved symptoms and helped in reduction of the size of tumor itself." (PMID 23110890, 2012). "Since a rise in estrogen levels induces prolactin synthesis and secretion, it subsequently leads on to lactotroph cell hyperplasia and an increase in tumor size." (PMID 23110890, 2012). "Our review of the literature (English language only) revealed few case reports of plurihormonal tumors with concomitant presence of ACTH and PRL/GH staining tumor cells." (PMID 23320206, 2012). "The first choice of treatment for prolactinomas are DA receptor agonists, being CAB the most effective one which inhibits PRL secretion and reduces tumor size." (PMID 21464994, 2011). "16K hPRL, the antiangiogenic 16-kDa N-terminal fragment of human prolactin was shown to prevent tumor growth and metastasis by modifying tumor vessel morphology." (PMID 22087289, 2011). "Two (7.4%) patients with functional (ACTH and GH/PRL) macroadenomas presented with tumor progression, 29.0 and 105.4 months after treatment, respectively." (PMID 22152397, 2011). "Consistent with previous prospective studies and case–control studies summarised in a recent review, we found that PRL levels were unrelated to two factors reflecting progression, tumour size, and lymph node metastases." (PMID 20736944, 2010). "In most patients with prolactinomas, treatment with dopamine agonists normalizes prolactin levels, restores gonadal function and fertility, and reduces the size of the tumor." (PMID 20478050, 2010). "Our laboratory recently demonstrated that curcumin inhibited growth and induced apoptosis in prolactin- and growth hormone-producing tumor cells." (PMID 20405005, 2010). "The GH-positive somatotroph tumour was positive in human GH staining and cell proliferation antigen staining, with moderate PRL staining." (PMID 19568241, 2009). "Following stereotactic radiosurgery, the tumor stabilized and prolactin almost normalized (22 ng/ml) on therapy." (PMID 19829805, 2009). "Subsequent injection of the host animals with two daily intrapituitary doses of 25 mg ganciclovir/kg for 7 days succeeded in partially reducing tumor size and serum PRL levels." (PMID 18218140, 2008). "Our results point to a putative clinical value of the semiquantitative PRL-3mRNA level assessment as a prognostic marker in stage III tumours receiving adjuvant therapy." (PMID 19002188, 2008). "Of concern is that 5% had prolactin levels over 2000 IU/l, which many clinicians would wish to investigate further to exclude a prolactin-secreting tumour." (PMID 17997803, 2007).
tumor (continued). "Increased secretion usually results from autonomous production by pituitary tumors (prolactinomas) and rarely, PRL-secreting tumors of the lung or kidneys." (PMID 23675050, 2007). "The PRL plasma mean levels of NMU tumour rats [T], were higher than in tumour homogenates [TH] (corresponding to the same group of rats and extraction time) 5.8 ± 1.2 ng/ml (n = 20); these results were statistically significant (P < 0.0005)." (PMID 18045456, 2007). "PRL is secreted not only by lactotrophic cells of the pituitary gland but also by a variety of other normal tissues and human tumours including malignant tumours of the lung, kidney, uterine, ovary, and breast." (PMID 15617576, 2004). "In the dimethylbenzanthracene (DMBA)-induced model in rats, in which tumor growth is predominantly dependent on prolactin for growth, tamoxifen and raloxifene show effective anti-tumor action." (PMID 15310397, 2004). "PRL was elevated in all Dukes stages and in all histological grades of the tumour whereas the rise in CEA was more pronounced in Dukes D. Out of 74 patients, 29% (21/74) developed recurrent disease and 31% (23/74) responded to the treatment." (PMID 1419646, 1992). "Because EP-stimulated tumours regressed after treatment with bromocriptine and dormant tumours in non-oestrogenized rats grew out after treatment with perphenazine, prolactin is the major growth-stimulating hormone in this model." (PMID 1911185, 1991). "The prolactin value in the plasma of the benign-tumour-bearing rats was about 27 times that of 6-month-old virgin rats, and similar to that of rats on the 7th day post partum." (PMID 7248153, 1981). "In an inbred strain of rats, tumour-induction rate was 6-4% and plasma prolactin concentration was 2-5 x lower than that found in a random-bred strain with a tumour-induction rate of 41-6%." (PMID 826265, 1976). "Cabergoline treatment led to PRL levels normalization and tumor shrinkage in the proband." (PMID 42008033, 2026). "We interpreted the elevated prolactin levels as a stalk effect despite the similar tumour volumes." (PMID 41351299, 2026). "For macroadenomas, as the cure rate or degree of fibrosis does not appear to be dependent on duration of DA use, CAB may be used to reduce tumor volume and normalize PRL levels before surgery." (PMID 41524959, 2026). "Another approach is to evaluate the ratio between prolactin levels and tumor volume or dimensions." (PMID 40960781, 2025). "According to the latest World Health Organization classification of PitNETs, a new subtype of tumor was mentioned: the mature plurihormonal Pit-1 lineage tumor, being similar with a mammosomatotroph adenoma (positive for GH and/or PRL), but in addition presenting immunopositivity also for TSH." (PMID 40643539, 2025). "Univariate linear regression showed that higher baseline PRL levels were positively predicted by male sex (β=0.45, p=0.001), optic chiasm compression (β=0.67, p<0.0001), sphenoid sinus invasion (β=0.43, p=0.002), and tumor size (β=0.80, p<0.0001)." (PMID 40995599, 2025). "In the future, through in-depth research on the functional mechanisms of these pRL factors, their roles in tumor occurrence, development, and immune microenvironment can be revealed, providing a scientific basis for the targeted treatment and development of new therapies for LUAD." (PMID 39834603, 2025). "Quantitative studies confirm the correlation between tumor size and PRL levels." (PMID 40599499, 2025). "Additionally, lower prolactin levels and tumor shrinkage after 6 months of treatment were predictive of subsequent normoprolactinemia and further tumor shrinkage, respectively." (PMID 40995599, 2025). "In line with this and also related to androgens signaling, prolactin dysregulation may increase androgen receptor (AR) signaling and tumor growth, posing to the prolactin antagonists as potential adjunct therapy." (PMID 39910005, 2025).
tumor (continued). "In summary, the interaction between HCMV and PRL reveals a complex mechanism that may affect immune responses and tumor behavior." (PMID 41476991, 2025). "However, low prolactin levels are also common in microprolactinomas due to the small tumor volume, and in large tumors, it is most often explained by stalk disconnection." (PMID 41303810, 2025). "In prolactinomas, serum PRL concentration typically correlates with tumor burden." (PMID 40599499, 2025). "The dissection of the PGE2-prolactin paracrine signaling axis between the tumor and stroma provides mechanistic insights into the pathways targeted by COX-2 inhibition, which is the most compelling and epidemiologically validated chemoprevention strategy for human PCa." (PMID 41583437, 2025). "In PRL-secreting PitNETs, DAs promote tumor regression/shrinkage due to the reduction of lactotroph cell size and to degenerative and necrotic changes in tumor cells, which may be followed by subsequent replacement fibrosis." (PMID 40725781, 2025). "In fact, OB-related leptin resistance and elevated inflammatory cytokines may amplify prolactin secretion, enhancing AR signaling and tumor progression." (PMID 39910005, 2025). "Interestingly, PRL can be proteolytically cleaved to form vasoinhibins, which counterbalance these effects through their antiangiogenic properties, highlighting the complex dual role of PRL in tumor vascularization." (PMID 41370498, 2025). "In addition, positive correlations were found between tumor maximum diameter and preoperative GH (p = 0.047) and PRL (p = 0.037) levels." (PMID 39707075, 2025). "Follow-up should aim to maintain normoprolactinemia, monitor the residual tumor via imaging (ideally with MRI at six months after initiating treatment, then annually if stable), and assess serum PRL levels every three to six months during the first year, then biannually thereafter." (PMID 40599499, 2025). "Despite these, he had refractory disease with markedly elevated prolactin levels and tumor growth." (PMID 41013821, 2025). "In one of our previous works on growth factor expression in PitNETs, we found that Vascular Endothelial Growth Factor (VEGF) mRNA is overexpressed in both tumor and endothelial cells but also in folliculo-stellate cells from PitNETs, especially PRL- and GH-secreting PitNETs." (PMID 41614857, 2025). "Furthermore, the treatment of prolactin-secreting PT with 15-dPGJ2 suppressed tumor growth and prolactin production." (PMID 40361329, 2025). "Additionally, PRL promotes tumor progression through proangiogenic effects, stimulating neovascularization and endothelial cell migration." (PMID 41370498, 2025). "Initial tumor size and prolactin-normalization are predictors of recovery outcomes." (PMID 40035956, 2025). "COX-2 mediates tumor-stromal prolactin signaling to initiate tumorigenesis." (PMID 41583437, 2025). "However, the stalk effect is temporary, as it resolves with tumor excision, and the prolactin level will drop postoperatively." (PMID 41303810, 2025). "This ectopic PRL behaves similarly to pituitary PRL and may exert local autocrine and paracrine immunomodulatory effects within the tumor microenvironment, contributing to cellular proliferation and immune escape." (PMID 41476991, 2025). "The low blood vessel density observed in PRL secreting PitNETs could be related to the existence of a 16 kDa fragment of prolactin, which exerts inhibitory influences on tumor angiogenic growth factors and endothelial cells." (PMID 41614857, 2025). "Tumor size has been a subject of debate regarding its relationship with serum PRL levels." (PMID 38572480, 2024). "On the other hand, prolactinomas that have not achieved remission after multiple visits may have a unique molecular composition, leading to higher prolactin levels during tumor growth." (PMID 38572480, 2024).
tumor (continued). "Prolactin levels measured immediately following resection surgery correspond to the existence of residual tumor, and an intensive resection, including removal of a layer of normal pituitary gland at the outer edge of the pseudocapsule is recommended to ensure complete excision." (PMID 39080760, 2024). "The interruption of tumour angiogenesis by inhibiting of PRL signalling may be a striking target for therapeutic interpolation." (PMID 39663784, 2024). "Moreover, small peptides, consisting of 3–7 amino acid residues, derived from human PRL potently inhibited angiogenesis and tumor growth (150 pm as IC50)." (PMID 39312470, 2024). "Collectively, ERα and PRL cooperatively promote downstream pro-tumor signals and BC proliferation." (PMID 38898487, 2024). "Cabergoline is the first-line treatment for PRL-secreting PitNETs, and in female patients who are often able to start treatment at an early stage, it is effective within a short period after initiation, with PRL normalization and tumor shrinkage rates of >90%." (PMID 38516477, 2024). "Thus, this current work provides new insight into how prolactin impacts cancer progression through its novel role in iron redistribution within the tumor microenvironment." (PMID 39201626, 2024). "However, 20–30% of patients treated with BRC and 10% of those treated with CAB exhibit resistance to DAs, which is marked by insufficient tumor shrinkage, or inadequate prolactin level control." (PMID 39684198, 2024). "The age at onset, prolactin values, tumor size, symptoms, and treatment were assessed." (PMID 38516477, 2024). "Here, we found that tumor PRL level predicted shorter RFS in patients treated with tamoxifen." (PMID 38898487, 2024). "Treatment aims to reduce tumor size and inhibit prolactin hypersecretion." (PMID 39684198, 2024). "In vivo, endothelial cell‐derived PRL is expected to be involved in the tumour microenvironment." (PMID 39663784, 2024). "Univariate and multivariate analysis were performed, but neither outcome—normalization of prolactin levels or tumor size reduction—was significantly associated with factors like sex, age, initial tumor size, treatment duration, or type of germline MEN1 PV." (PMID 39439563, 2024). "Prolactin is a peptide hormone produced by the anterior pituitary gland, but evidence also shows non-lactotroph prolactin can be produced by cancer cells and such prolactin within the tumor microenvironment is positively correlated to tumor progression." (PMID 39201626, 2024). "Given that three-dimensional tumor spheroids could better simulate in vivo conditions, this finding indicated that N8 has the potential to inhibit the effects of PRL in a physiological context." (PMID 38898487, 2024). "Cabergoline is more than 90% effective in normalizing prolactin levels and decreasing tumor size, with the advantage of being given only twice weekly; unfortunately, it is expensive, not readily available in the country, and must be imported from other countries like India." (PMID 38535157, 2024). "During the 12-month follow-up, methylation profiling and prolactin blood assessments showed that methylation markers clustered with NT specimens, which coincided with prolactinemia normalization, indicating successful tumor control after surgery." (PMID 39876960, 2024). "On the one hand, this could be due to tumors developing resistance to DAs, resulting in uncontrolled tumor growth and continued abnormal PRL secretion." (PMID 38572480, 2024). "Subsequently, we generated a stable MCF7-TAMR-TETON-PRL cell line to investigate if N8 could inhibit the effect of PRL that is produced endogenously by tumor cells." (PMID 38898487, 2024). "Furthermore, we providedin vivoevidence that pTyr-PAK1 stimulates PRL-induced tumor metastasis in mice." (PMID 38660565, 2024).
tumor (continued). "However, as macrophages are pre-treated with prolactin for 2 days before the co-culture with tumor cells for iron transfer, some macrophages shift into M2-like phenotype, thereby exhibiting iron transfer capacity." (PMID 39201626, 2024). "The addition of EVE to CAB markedly decreased PRL levels and tumor regression." (PMID 39736867, 2024). "Indeed, unlike the DA-resistant group, in which a sub-set of patients are characterized by very high prolactin and large tumor size, in the AIPvar group prolactin levels increased little with rising tumor volume, which is unusual for prolactinomas in general." (PMID 37711900, 2023). "Therefore, our results emphasize the value of preoperative DA treatment in cystic prolactinoma patients for reducing tumor size or preoperative PRL levels to a certain extent." (PMID 37143054, 2023). "More patients in the NTL group had prolactin (+) cells after IHC staining; this may be explained by the fact that surgery can remove most of the prolactin-secreting component in the tumor mass so the cells could be found in the staining." (PMID 37886642, 2023). "However, postsurgical remission rates are lower in cases with markedly elevated preoperative prolactin levels, larger tumor size, extrasellar extension, or cavernous sinus invasion." (PMID 37143698, 2023). "However, a discrepancy between tumor size and PRL levels warrants serial dilutions of PRL to exclude the “hook effect”." (PMID 37403202, 2023). "Overall, participant and tumor characteristics were similar by prolactin-related tumor expression." (PMID 36882838, 2023). "In addition, DA can indirectly affect tumor growth by regulating the production and release of prolactin, which regulates the function of NK cells and lymphokine-activated killer cells." (PMID 37215113, 2023). "In patients treated primarily with DA (n = 79), reduction of serum PRL to <2×ULN or reduction of the maximum tumor diameter by 20% after the first year of treatment were both associated with a combined response at the last follow-up [both univariate and multivariate analyses]." (PMID 37403202, 2023). "In 1 study, 2 out of 71 patients with giant prolactinomas maintained normal PRL and tumor response after DA withdrawal, but it is unclear whether these patients had received DA monotherapy or multimodal therapy." (PMID 37403202, 2023). "Testosterone aromatizes to estradiol, which might lead to lactotroph hyperplasia with an entailing increase in PRL and tumor size." (PMID 37403202, 2023). "Tumour-related cell death can be regulated through autophagy and apoptosis by targeting PRL/PRLR, while the combination of PRL and PRLR has a dose–response relationship: a low concentration of PRL promotes the secretion of PRLR, whereas a high dose of PRL inhibits PRLR." (PMID 37833858, 2023). "Males with prolactinomas had larger tumor sizes and higher serum PRL levels than females." (PMID 37664314, 2023). "We consider that the ideal approach to obtain more information about GH/PRL tumors would be carrying out multicentric studies that follow the latest WHO classification recommendations for tumor classification, combining molecular and clinical information to determine the outcomes of these patients." (PMID 37762304, 2023). "Of these, six tumours expressed prolactin, but none caused high serum prolactin (PRL) at presentation." (PMID 37851558, 2023). "Furthermore, our study also indicated that tumor size and preoperative PRL levels < 200 ng/ml were independent predictors for postoperative remission in cystic prolactinomas using multivariate logistic regression analysis." (PMID 37143054, 2023). "Additionally, serum prolactin decreased to 122 ng/mL, and MRI showed a reduction in tumor size along with a decrease in the cystic and necrotic components of the tumor." (PMID 37529607, 2023).